ACHE (acetylcholinesterase (Yt blood group))
Diseases named in the same sentence as ACHE in open-access papers (continued):
Sharing a sentence is not in itself a finding about the gene and the disease.
Alzheimer disease (continued). "The significant acetylcholinesterase (AChE) inhibitory activity, especially in the polar extracts, suggests potential applications in the treatment of Alzheimer’s disease and other neurodegenerative conditions." (PMID 40572099, 2025). "Donepezil, a well-known cholinesterase inhibitor used in treating Alzheimer’s disease, serves as the positive control, exhibiting nearly complete inhibition of both enzymes (97.59% for AChE and 100% for BChE)." (PMID 39885008, 2025). "Following oral administration of 1–6 mg rivastigmine twice daily, AChE activity is suppressed in a dose-dependent fashion within the CSF of individuals with Alzheimer’s disease." (PMID 40553197, 2025). "A study of embryonic mouse AChE found it to be potentially analogous to pathological AChE in Alzheimer’s disease, due to it showing altered PAS and reduced binding affinity." (PMID 41155192, 2025). "Potential anti-Alzheimer’s disease capacity was evaluated by AChE and BChE enzyme inhibition assays." (PMID 40868920, 2025). "Marmelosin improves neurotransmission and lessens Alzheimer's disease symptoms by raising acetylcholine (ACh) levels through AChE inhibition." (PMID 40535825, 2025). "Other data also suggested that the combination of quercetin and galantamine hydrobromide, an anticholinesterase and neurocognitive-enhancing drug commonly used for Alzheimer′s disease, has a synergistic inhibition effect on AChE." (PMID 40722302, 2025). "The inhibiting activity against AChE, an enzyme involved in the pathogenesis of Alzheimer’s disease (AD), was evaluated for the more lipophilic extracts obtained with ethyl acetate." (PMID 41295163, 2025). "The inhibitory effect on AChE and BChE further positions MLs as a natural source for treating Alzheimer's disease and similar neurodegenerative disorders." (PMID 40351366, 2025). "Using AChE inhibitors is one of the main current pharmacological alternatives for the treatment of Alzheimer's Disease." (PMID 40231522, 2025). "AChE inhibitors are vital in treating symptoms of neurodegenerative conditions such as Alzheimer’s disease, which are characterized by a significant decline in cholinergic function." (PMID 40649363, 2025). "AChE activity increases as a result of Alzheimer’s disease, while AChE inhibitors help to alleviate Alzheimer’s symptoms." (PMID 40284497, 2025). "Our findings are significant because AChE inhibition represents a key mechanism in the therapeutic intervention of neurodegenerative diseases, such as Alzheimer’s disease." (PMID 40871477, 2025). "In this study, the structural parameters and inhibitory potential of specific organotin(IV) compounds, with and without the SBA-15~Cl carrier, were evaluated against key enzymes involved in the pathophysiology of Alzheimer’s disease: AChE, COMT, and MAO-B." (PMID 40559280, 2025). "Several studies have also reported that certain plants rich in phenolic compounds, such as kaempferol, exert an inhibitory activity on AChE and appear to have protective effects in the face of Alzheimer's disease." (PMID 40792047, 2025). "Rivastigmine, classified as a carbamate-type dual inhibitor of AChE and BuChE, is commonly utilised as a cholinergic agent in the symptomatic management of Alzheimer’s disease; its efficacy and tolerability in this condition were reviewed in a previous study." (PMID 40553197, 2025). "The strategy for treating Alzheimer’s disease involves controlling the level of acetylcholine, a neurotransmitter in cholinergic synapses, by blocking the degradation of acetylcholine using AChE inhibitors." (PMID 40284441, 2025). "AChE plays a crucial role in the pathogenesis of Alzheimer’s disease (AD) by influencing inflammation, apoptosis, oxidative stress, and protein aggregation." (PMID 40429850, 2025).
Alzheimer disease (continued). "Galanthamine, an acetylcholinesterase (AChE) inhibitor, is an Amaryllidaceae alkaloid that has emerged as a valuable therapeutic agent in the palliative management of Alzheimer’s disease (AD) symptoms following its FDA approval in 2001." (PMID 40941958, 2025). "AChE inhibition is a well-established therapeutic strategy for Alzheimer’s disease (AD), the most prevalent ND, as it aims to restore impaired cholinergic function." (PMID 40952625, 2025). "Alzheimer's disease (AD) is an irreversible, fatal neurodegenerative disorder in the elderly, and current treatments mainly rely on single-target acetylcholinesterase (AChE) inhibitors with limited effects on disease progression." (PMID 41356836, 2025). "Alzheimer’s disease (AD) is characterized by cholinergic deficits and neuronal damage, making acetylcholinesterase (AChE) a crucial therapeutic target." (PMID 41011582, 2025). "Donepezil (DPZ) is an Alzheimer’s disease (AD) drug that promotes cholinergic neurotransmission and exhibits excellent acetylcholinesterase (AChE) selectivity." (PMID 40870981, 2025). "Alzheimer Disease (AD) - BChE complements AChE activity in the central nervous system by breaking down ACh and maintaining cholinergic signaling." (PMID 40612057, 2025). "Individuals suffering from Alzheimer’s disease (AD) use current therapy targeting acetylcholine levels in CNS synapses by applying selective AChE inhibitors: donepezil, rivastigmine and galantamine." (PMID 38928014, 2024). "With the progression of Alzheimer’s disease, AChE levels decrease, and BChE levels increase, while in healthy brains, AChE is the predominant hydrolyzing enzyme." (PMID 39796014, 2024). "The plant constituents are important in decreasing the development of Alzheimer's disease by inhibiting BChE and AChE." (PMID 39698089, 2024). "Inhibiting AChE would result in elevated amounts of ACh in the brain, leading to enhanced cholinergic connections in individuals with Alzheimer’s disease." (PMID 39453222, 2024). "AChE inhibitors are used to treat Alzheimer’s disease because they help increase acetylcholine levels in the brain." (PMID 38256704, 2024). "Since some AChE inhibitors are used for neurological conditions (donepezil in the treatment of Alzheimer’s disease and pyridostigmine of myasthenia gravis), their cardiovascular effects have been investigated." (PMID 39117958, 2024). "To date, three of the four drugs have been approved for the treatment of Alzheimer’s disease as an AChE inhibitor." (PMID 38338420, 2024). "Therapy incorporatingH3R antagonists with additional AChE/BuChE inhibitory effectsmay improve cognitive functions in Alzheimer’s disease." (PMID 38440987, 2024). "AChe has been identified as the leading therapeutic target for symptomatic treatment of Alzheimer’s disease." (PMID 39456335, 2024). "Inhibition of AChE is currently under investigation in Alzheimer’s disease and vascular dementia, emphasizing the importance of ChE in neurological diseases." (PMID 38321383, 2024). "In Alzheimer’s disease, the production of acetylcholine is diminished, so the inhibition of AChE helps maintain the normal levels of ACh." (PMID 39000508, 2024). "Various natural inhibitors of the AChE, BChE, α-glucosidase, and α-amylase enzymes are useful in managing ailments, especially diabetes and Alzheimer’s disease, and the search for more of such compounds is an important domain in medicinal chemistry." (PMID 38893333, 2024). "The inhibition of AChE has gained attention as a therapeutic strategy for neurological disorders including Lewy body dementia and Alzheimer’s disease." (PMID 39765732, 2024). "Research on acetylcholinesterase (AChE) in chronic Alzheimer’s disease has emerged as a potential area of study." (PMID 38542869, 2024). "In rats with STZ-induced Alzheimer's disease, there was a noticeable increase in AChE activity in the hippocampus and frontal cortex compared to the sham control group." (PMID 38688962, 2024).
Alzheimer disease (continued). "Reduced concentrations of AChE are frequently noted in neurodegenerative disorders like Alzheimer’s disease and various forms of dementia." (PMID 38337955, 2024). "A typical example is huperzine A produced by Huperzia serrata, an AChE inhibitor to treat early- to mid-stage Alzheimer’s disease." (PMID 38535204, 2024). "Specifically, the ‘Aurora’ rosehips demonstrate potent antioxidant properties and a moderate inhibitory effect on AChE, which is relevant for Alzheimer’s disease research." (PMID 39456335, 2024). "Since AChE is a representative biomarker for Alzheimer’s disease (AD), the TDN-aptamer complex has shown its potential as a sensing platform in real samples, namely, AD patients’ sera, and the detection results were confirmed by ELISA analysis." (PMID 39727892, 2024). "BChE is predominantly expressed in white matter and glial cells (specifically astrocytes), while AChE is localized in neuronal areas that are crucial for cognition and behavior, regions that undergo functional impairment in Alzheimer’s disease." (PMID 39596378, 2024). "They evaluated them for their AChE and BuChE inhibitory activities, targeting potential treatments for Alzheimer’s disease." (PMID 39407697, 2024). "In a recent study by Liu, the authors demonstrated significant anti-Alzheimer’s disease potential by testing a variety of bioactive compounds from A. membranaceus, which was also confirmed by molecular docking targeting the AChE enzyme." (PMID 38543134, 2024). "Molecular modeling of AChE has been instrumental in designing new drugs for the treatment of Alzheimer’s disease, a condition characterized by a decrease in brain acetylcholine levels." (PMID 39065009, 2024). "AChE inhibitors are, therefore, valuable in treating neurodegenerative injuries, such as Alzheimer’s disease." (PMID 39339433, 2024). "By combining the N-BP motif with other pharmacophores, researchers design molecules that can not only inhibit AChE but also interact with other targets, such as β-amyloid plaques and tau tangles, which are hallmarks of Alzheimer’s disease." (PMID 39598703, 2024). "Despite some limitations being seen in AChE inhibitors, ongoing research remains dedicated to finding innovative and more effective treatments for Alzheimer’s disease." (PMID 38542869, 2024). "J.M.Gillett, which showed a weak inhibitory effect on acetylcholinesterase (AChE) and monoamine oxidases (MAO) A and B, which are associated with Alzheimer’s disease." (PMID 39201264, 2024). "AChE also contributes to inflammatory reactions, Aβ complex formation, and cytotoxicity mechanisms in Alzheimer’s disease." (PMID 39661258, 2024). "Due to AChE’s ability to mitigate Ach hydrolysis and the resultant neuron-to-neuron communication, inhibitors of AChE have found usage as Alzheimer’s Disease (AD) medication." (PMID 38792196, 2024). "Galanthamine is an acetylcholinesterase (AChE) inhibitor used to alleviate the symptoms of Alzheimer’s disease (the disease itself is incurable) and other neurodegenerative diseases." (PMID 39771275, 2024). "Succinimide compounds seem to be 2.4–2.3 times more powerful AChE inhibitors than rivastigmine, which is a commonly used drug for Alzheimer’s disease and has an IC50 value of 71,000 μM." (PMID 38920979, 2024). "There are two types of cholinesterases, acetylcholinesterase (AChE) and butyrylcholinesterase (BChE), that are attractive as candidate targets for the treatment of Alzheimer’s disease." (PMID 38732642, 2024). "The inhibition of AChE has emerged as a promising therapeutic approach for the management of neurological disorders such as Lewy body dementia and Alzheimer’s disease." (PMID 39765732, 2024). "The obtained inhibition values were compared to those of 9-amino-1,2,3,4-tetrahydro-acridine hydrochloride (tacrine), a commonly used AChE inhibitor in Alzheimer’s disease treatment." (PMID 39765812, 2024).
Alzheimer disease (continued). "The present research suggests that taxifolin has a strong ability to bind and inhibit AChE and BChE and could be used to manage neuron-associated problems; however, further research is required to explore taxifolin’s neurological therapeutic potential using animal models of Alzheimer’s disease." (PMID 38338420, 2024). "Cholinesterase enzymes, namely, acetylcholinesterase (AChE) and butyrylcholinesterase (BChE), hold pivotal significance in Alzheimer’s disease (AD) treatment." (PMID 38543134, 2024). "AChE and BChE are both well-known enzymatic targets for treatment of Alzheimer’s disease (AD), and AChE and BChE inhibitors (AChEI and BChEI, respectively) have long been of interest." (PMID 38059272, 2024). "Inhibition of acetylcholinesterase (AChE) is a crucial target in the treatment of Alzheimer’s disease (AD)." (PMID 38833492, 2024). "In this article, we present the design and synthesis of amino-7,8-dihydro-4H-chromenone derivatives as possible inhibitors of acetylcholinesterase (AChE) and butyrylcholinesterase (BChE) for the management of Alzheimer’s disease (AD)." (PMID 38600537, 2024). "Acetylcholinesterase (AChE) holds significance in Alzheimer's disease (AD), where cognitive impairment correlates with insufficient acetylcholine levels." (PMID 39483377, 2024). "The Amaryllidaceae family is known for its ornamental potential and the ability to synthesize several alkaloids, including galantamine and lycorine, and potent acetylcholinesterase (AChE) inhibitors, used to alleviate the symptoms of Alzheimer’s Disease (AD)." (PMID 38475416, 2024). "The inhibition of (AChE) is presently a common pharmacological approach for some diseases, including; Alzheimer’s disease (AD), some eye diseases, postoperative use, and myasthenia gravis." (PMID 38429330, 2024). "These structures present the new scaffold of 1,2,3-triazolium salts for drug development as the current therapy in Alzheimer’s disease (AD) are selective AChE inhibitors, while in Parkinson’s and all stages of AD, non-selective inhibitors of ChE are preferred." (PMID 39595567, 2024). "Acetylcholinesterase (AChE) and butyrylcholinesterase (BChE) are vital enzymes involved in the progression of Alzheimer’s disease (AD)." (PMID 39338986, 2024). "In Alzheimer’s disease, inhibition of AChE plays a crucial role in increasing cholinergic transmission in the brain and lowering amyloid beta peptide (Aβ) aggregation and the generation of neurotoxic fibrils." (PMID 37400624, 2023). "For example, Huperzine A is a potent inhibitor of acetylcholinesterase (AChE) and shows promise in the treatment of Alzheimer’s disease (AD)." (PMID 37687022, 2023). "AChE inhibitors are used to treat Alzheimer’s disease, a neurodegenerative disorder characterized by progressive cognitive decline and memory loss." (PMID 37932428, 2023). "Similar to these results, needle essential oils from various Pinus species showed potential beneficial effects in the treatment of Alzheimer’s disease by significantly inhibiting AChE activity in vitro." (PMID 37762386, 2023). "Synthesized AChE inhibitors are promising candidates for the development of new drugs for Alzheimer’s disease, as they can target multiple aspects of the disease pathogenesis and offer better efficacy and safety profiles than the currently available drugs." (PMID 37932428, 2023). "AChE and BuChE inhibitors have been developed and used to treat Alzheimer’s disease by boosting cholinergic neurotransmitter activity in the brain, thereby reducing AD symptoms." (PMID 37049419, 2023). "Irreversible AChE inhibitors are used as insecticides while reversible inhibitors are useful for several diseases such as Alzheimer’s disease." (PMID 36695002, 2023). "Skimmianine shows potential in the treatment of Alzheimer’s disease due to its ability to inhibit acetylcholine esterase (AChE) and the production of nitric oxide (NO), which can influence inflammation within the nervous tissue." (PMID 37628986, 2023).
Alzheimer disease (continued). "By targeting drugs with multiple actions, such as inhibitors of acetylcholinesterase (AChE) and butyrylcholinesterase (BuChE), this approach is specifically beneficial for treating Alzheimer’s disease." (PMID 38139795, 2023). "The inhibitors of the AChE enzyme are now the first-line drugs in the treatment of dementia and Alzheimer’s disease (AD)." (PMID 37759757, 2023). "As a result, people with Alzheimer’s disease must suppress both major forms of cholinesterase, AChE and BChE, in order to restore acetylcholine levels." (PMID 37400624, 2023). "In recent times, research has unveiled their capacity to inhibit acetylcholinesterase (AChE) and/or butyrylcholinesterase (BChE), which are enzymes that play pivotal roles in neurodegenerative disorders such as Alzheimer’s disease." (PMID 37894690, 2023). "DL controlled Alzheimer’s disease progression through the cholinergic enzymes (AChE and BChE) and the β-amyloid forming enzyme (BACE-1)." (PMID 38066118, 2023). "This is the first chemical and biological report about the species C. variegatus, which showed interesting structural diversity and high activity against AChE, a relevant enzyme in the cholinergic therapy for Alzheimer’s disease." (PMID 37513280, 2023). "Acetylcholinesterase (AChE) inhibitors are one of the most effective therapeutics for Alzheimer disease, as they alter the excess of synaptic AChE and increase acetylcholine levels." (PMID 37369580, 2023). "Another virtual screening model was established to successfully find acetylcholinesterase (AChE) inhibitors with the ability of protecting human neuroblastoma cells from Aβ-induced injury for Alzheimer’s disease treatment." (PMID 36768218, 2023). "From this vantage point, blocking the enzyme responsible for producing AChE has proven to be an efficient Alzheimer’s disease treatment." (PMID 36985342, 2023). "Among the proteins of therapeutic interest in Alzheimer’s disease and capable of activating a pleiotropic prodrug to form an active ingredient, AChE and butyrylcholinesterase (BuChE) are prime targets." (PMID 37896142, 2023). "For the enzymes involved in Alzheimer’s disease (AChE, BChE, and BACE-1), DL exhibited the highest C score of 0.891." (PMID 38066118, 2023). "We can extrapolate adverse effects of these compounds from those of AChE inhibitors used in Alzheimer’s disease treatment and medications used for smoking cessation (nicotine replacement therapy and varenicline)." (PMID 37895835, 2023). "The active extracts have potential to be used for the development of functional foods with positive effects on Alzheimer’s disease owing to their high AChE inhibition activity." (PMID 37174291, 2023). "Several drugs have been approved by the food and drug administration (FDA) for patients with Alzheimer disease including galantamine and Donepezil which are selective for AChE while rivastigmine and tacrine were found to inhibit both BuChE and AChE." (PMID 37513821, 2023). "Restoring short- and long-term memory in patients with Alzheimer’s disease using therapeutic approaches that target AChE and BuChE has been observed." (PMID 37368609, 2023). "Inhibition of AChE has been of great interest as a therapeutic strategy for a range of neurological disorders, particularly Alzheimer’s disease (AD)." (PMID 37110646, 2023). "Different rosemary extracts also showed anti-acetylcholinesterase (AChE) activity and play an important role in some neurodegenerative ailments such as Alzheimer’s disease, dementia, and Parkinson’s disease." (PMID 37627628, 2023). "The results of AChE are relevant in researching treatments for Alzheimer disease; Benny and Tomas in 2019 reported the neuroprotective effect of EO and their pure compounds." (PMID 37049672, 2023). "Graphical CNNs were employed, with images of molecule fingerprints as the input, in the search for new AChE inhibitors for the treatment of Alzheimer’s disease." (PMID 36770990, 2023).